BIRC5 (baculoviral IAP repeat containing 5)
Diseases named in the same sentence as BIRC5 in open-access papers (continued):
Sharing a sentence is not in itself a finding about the gene and the disease.
melanoma (29 papers, 2007 to 2026). A malignant, usually aggressive tumor composed of atypical, neoplastic melanocytes. "In this review, BIRC5 gene mutations have been associated with shorter survival in glioma, lung, ovarian, melanoma and endometrial cancers (5 studies)." (PMID 35444210, 2022). "We utilized a validated commercial antibody against Survivin, an anti-apoptotic protein encoded by BIRC5, to perform immunostaining on a melanoma progression tissue microarray (TMA)." (PMID 20520718, 2010). "Cox analysis implied that higher levels of CD4+ T cell (HR = 20.246, P = 0.049), macrophage (HR = 12.960, P = 0.033), BIRC5 expression (HR = 1.321, P = 0.001) and lower levels of neutrophil (HR < 0.001, P = 0.020) were risk factors for prognosis in melanoma patients." (PMID 33072607, 2020). "We obtained the risk scores of patients with melanoma: risk score = (−0.379123977 × expression of IFNG) + (−0.662084468 × expression of DAPK2) + (0.342818269 × expression of ATG9B) + (0.406559238 × expression of PTK6) + (0.807218069 × expression of BIRC5) + (0.364523721 × expression of EGFR)." (PMID 36690663, 2023). "Boxplots created with the GEPIA2 tool revealed that the expression of BIRC5 was significantly increased in melanoma patients compared with normal control tissue samples." (PMID 41227355, 2025). "Melanoma patients were stratified according to the expression values of BIRC5 into high (above median BIRC5 expression) and low (below median BIRC5 expression) groups." (PMID 41227355, 2025). "These include some canonical melanoma tumor-suppressive genes such as BRD9 and CDKN2A/CDKN2B, and several critical melanoma oncogenes like BIRC5 and YAP1." (PMID 37904237, 2023). "A total of 10137 melanoma cells were clustered into 7 subtypes (C0 Melanoma BIRC7, C1 Melanoma CDH19, C2 Melanoma EDNRB, C3 Melanoma BIRC5, C4 Melanoma CORO1A, C5 Melanoma MAGEA4, C6 Melanoma GJB2)." (PMID 37435067, 2023). "Here, we report the ability of PEL and EPI to cause apoptosis in melanoma cells through the contemporaneous increase in pro-apoptotic BAX mRNA expression and decrease in the anti-apoptotic BCL-2, BIRC-5, and MCL1 mRNA expression." (PMID 35877720, 2022). "Among the other tested genes, survivin/BIRC5 showed as well-promising results as a prognostic marker in canine melanoma." (PMID 34485433, 2021). "Meanwhile, the functions of LTBP4 overexpression in inhibiting the expression of cleaved caspase-3 and E-cadherin and inhibiting that of Ki67, CTGF, Cyr61 and Birc5 in melanoma cells were abolished by YAP1 overexpression or MST1 overexpression." (PMID 35252214, 2021). "The BIRC5 is rarely expressed in normal tissues but overexpressed in most types of tumors including melanoma, and the expression level is correlated with aggressive disease progression and poor clinical outcomes." (PMID 33072607, 2020). "CDK4/6 inhibition in melanoma cells resulted in apoptosis associated with deregulation of BCL2, BCL2L1, BIRC5 and BIM." (PMID 30349650, 2018). "BIRC5 is expressed in embryonic and fetal tissues, many types of neoplasias, including melanoma, and cannot be detected in differentiated adult tissues." (PMID 22649681, 2011). "Among the tested genes, only BIRC5 expression in melanoma patients could be used as a statistically significant prognostic marker of poor outcome (HR 1.22; 95% CI: 1.05–1.42; p-value 0.01)." (PMID 41227355, 2025). "Melanoma patients with high expression of BIRC5, EGFR, and ATG9B had a worse prognosis." (PMID 36690663, 2023). "BIRC5 immunotherapy-related clinical trials have been applied in patients with colorectal cancer, malignant glioma, and melanoma." (PMID 35664300, 2022).
melanoma (continued). "In addition, the effects of LTBP4 overexpression on inhibiting CTGF, Cyr61 and Birc5 expression, promoting the apoptosis, and inhibiting the metastasis and proliferation of melanoma cells were reversed by the overexpression of YAP1 or MST1." (PMID 35252214, 2021). "These properties of BIRC5/survivin made it a subject of dendritic cell-based vaccination and anti-tumor sensitization protocols, which are to be tried out in clinical trials for patients with advanced solid tumors including BC, melanoma, glioma, and pancreatic and colon cancers." (PMID 34064473, 2021). "Among downregulated genes after ICG-001 treatment, BIRC5, EZH2, E2F1, and other oncogenes related to melanoma were found." (PMID 41227355, 2025). "In this study, the transcript levels of IAP genes including NAIP (BIRC1), BIRC2 (CIAP1), BIRC3 (CIAP2), BIRC5 (Survivin), BIRC6 (Apollon), and XIAP (BIRC4) in UA-treated A-375 melanoma cells were investigated." (PMID 39473730, 2024). "The same trend was observed in melanoma cells treated with EPI, which significantly increased the mRNA expression of BAX and decreased the mRNA expression of BCL2, BIRC5, and MCL-1." (PMID 35877720, 2022). "Another important player in the apoptotic process is BIRC5 (survivin), a member of the inhibitor of apoptosis protein (IAP) family, involved in melanoma drug resistance." (PMID 35877720, 2022). "CTGF, Gyr61, and Birc5 expression levels were reduced, YAP1 phosphorylation was inhibited, and YAP1 was translocated from the cytoplasm to the nucleus in melanoma cells treated with TGF-β1." (PMID 35252214, 2021). "Copy number gains of three BIRC genes (BIRC2, BIRC3, and BIRC5) were identified in melanoma, while miR-195-5p/− 218-5p, and not genetic/epigenetic aberrations, was correlated in high BIRC5 levels in gastric cancer." (PMID 35331169, 2022). "Concordantly with the gene modulation results, a significant reduction in miR-214-3p, targeting BAX, and a significant up-regulation of miR-16-5p, targeting BCL2 and BIRC5, and of miR-193a-3p, targeting MCL-1, were observed in PEL and EPI -treated melanoma cells." (PMID 35877720, 2022). "Additionally, the GEO dataset GSE50509, which contains transcriptomic data for melanoma patients who experienced disease progression after treatment with BRAFV600 inhibitors (prog) matched with pre-treatment melanoma samples (pre), was analyzed to assess changes in BIRC5 expression." (PMID 41227355, 2025).
neuroblastoma (27 papers, 2006 to 2024). Neuroblastoma (NB) is the most common solid, extracranial childhood tumor. "In order to obtain the optimal results, multivariate COX regression analysis was performed on 6 key-target genes, and 3 genes associated with neuroblastoma were identified, i.e., BIRC5, TIMP2 and CASP9." (PMID 38982456, 2024). "Elevated expression of BIRC5/survivin, a protein crucial for cell division, is linked to unfavorable outcomes in neuroblastoma (NB), a prevalent pediatric tumor." (PMID 38136322, 2023). "Increased expression of BIRC5/survivin, a crucial regulator of the mitotic spindle checkpoint, is associated with poor prognosis in neuroblastoma (NB), the most common extracranial tumor of childhood." (PMID 38136322, 2023). "Neuroblastoma models have shown that one cause of survivin overexpression is BIRC5 gene amplification at 17q25." (PMID 31929540, 2020). "Over-expression of BIRC5 has been associated with aggressive forms of neuroblastoma and other several types of cancer." (PMID 28467792, 2017). "High expression of BIRC5 was associated with poor clinical outcomes in many cancers, including BC, hepatocarcinoma, pancreatic cancer, esophageal carcinoma, and neuroblastoma." (PMID 36358602, 2022). "BIRC5 is a well-established contributor to cancer progression in several cancers, including neuroblastoma." (PMID 38049564, 2024). "Prior research has demonstrated that BIRC5 is notably up-regulated in neuroblastoma, and the down-regulation of BIRC5 induces apoptosis in neuroblastoma through mitotic catastrophe." (PMID 38982456, 2024). "IGF2BP1 is a post-transcriptional enhancer of oncogene expression, including MYCN and BIRC5, in various cancers with exceeding expression in Chr 17q unbalanced neuroblastoma." (PMID 37246217, 2023). "In sum, this suggested that IGF2BP1 is a potent, druggable oncogene in neuroblastoma synergizing with MYCN in a transcriptional/post-transcriptional feedforward loop resulting in the upregulation of oncogenes like the 17q-located BIRC5." (PMID 37246217, 2023). "Many of these, e.g. NME1, PYCR1, TK1, BIRC5 and TOP2A, are located on Chr 17q, are upregulated in unfavorable neuroblastoma and associated with poor patient outcome." (PMID 37246217, 2023). "IGF2BP1-driven malignancies are reminiscent to human high-risk neuroblastoma, including 2p/17q-syntenic chromosomal gains and upregulation of Mycn, Birc5, as well as key neuroblastoma circuit factors like Phox2b." (PMID 37246217, 2023). "While the mechanism of action of YM155 is disputable, a recent study confirmed BIRC5 as a critical YM155 target in neuroblastoma." (PMID 36612203, 2022). "BIRC5 not only is frequently amplified at chromosome 17q in neuroblastoma but also plays an important role in regulating apoptosis and the mitotic spindle checkpoint." (PMID 36612203, 2022). "A previous study found that miR-203 inhibits ovarian tumor metastasis by targeting BIRC5/survivin and that BIRC5/survivin can also serve as a target for glycolysis inhibition in high-stage neuroblastoma." (PMID 33109128, 2020). "Anti-apoptotic protein BIRC5 was recently shown to shift neuroblastoma cells from oxidative phosphorylation to anaerobic glycolysis, increasing their resistance to chemotherapy." (PMID 28467792, 2017). "In our study, we demonstrate a significant down-regulation of BIRC5 in the four neuroblastoma cell lines by qPCR analysis." (PMID 28467792, 2017). "At least two genes, survivin/BIRC5 and nm23/NME1, mapping to 17q gain regions, have been implicated contributing to the aggressive phenotype of neuroblastomas." (PMID 28055978, 2017). "Promising results obtained by BIRC5 inhibitors in pancreatic cancers with complete remission of liver metastases make BIRC5 a potential target of chemotherapy in neuroblastoma." (PMID 28467792, 2017). "Besides, multivariate COX regression analysis was carried out to obtain three genes related to the prognosis of neuroblastoma, namely BIRC5, TIMP2 and CASP9." (PMID 38982456, 2024).
neuroblastoma (continued). "Scientists discovered that the high activation of BIRC5 depressed the respiration of mitochondria and induced its fragmentation, finally led to Foxo3-dependent cell apoptosis by preventing reactive oxygen species accumulation, in neuroblastoma." (PMID 35461228, 2022). "BIRC5 has also been reported to enhance aerobic glycolysis in neuroblastoma." (PMID 36293001, 2022). "The microarray module 2 contains gene BIRC5, which previously found to be strongly overexpressed in neuroblastoma tumor samples and correlate to a poor prognosis, which could be a potential therapeutic target." (PMID 31443736, 2019). "BIRC5/Survivin as a target for glycolysis inhibition in high-stage neuroblastoma." (PMID 28516419, 2017). "In vitro studies verified puerarin's impact on BIRC5, TIMP2, and CASP9 expression, inhibiting proliferation in neuroblastoma SH-SY5Y cells." (PMID 38982456, 2024). "Next to IGF2BP1, this analysis unraveled top-ranking of BIRC5 and TOP2A among common essential as well as NME1 among neuroblastoma essential Chr 17q genes." (PMID 37246217, 2023). "We first treated neuroblastoma BE2C cells with the selective EZH2 inhibitor EPZ5687 or GSK343 and the BIRC5 inhibitor YM155." (PMID 36612203, 2022). "For example, the expression footprint of six neuroblastoma-related genes (ALK, BIRC5, CCND1, MYCN, NTRK1 and PHOX2B) have been used to differentiate neuroblastoma molecular subtypes." (PMID 34842635, 2021). "We specifically studied MYCN, MYBL2, BIRC5, BARD1 and AURKA, poor prognosis markers of neuroblastoma, and CCNA2 and CCNE1 genes, involved in general carcinogenesis." (PMID 28467792, 2017). "Citalopram drastically decreased the expression of MYBL2, BIRC5 and BARD1 poor prognosis factors of neuroblastoma with fold-changes of -107 (p<2.26 10−7), -24.1 (p<5.6 10−9) and -17.7 (p<1.2 10−7)." (PMID 28467792, 2017). "In human neuroblastoma cell lines STAT3 mediates the inhibition of apoptosis by IL-6 and the up-regulation of BIRC5 and BCL2L1 by IL-6 two actions probably involved in the drug resistance of some human neuroblastomas." (PMID 28467792, 2017). "Furthermore, they identified that some special genes such as MAD2L, CCNB1 and BIRC5, which had a close relationship with ERCC6L were involved in the cell cycle pathway, thus ERCC6L may play an important role in neuroblastoma." (PMID 32891122, 2020).
glioma (25 papers, 2017 to 2025). A benign or malignant brain and spinal cord tumor that arises from glial cells (astrocytes, oligodendrocytes, ependymal cells). "Previous studies have shown that BIRC5 is highly expressed in glioma and associated with poor prognosis in patients with glioma." (PMID 37340587, 2023). "The increased expression of BIRC5 was associated with markers of tumor histological malignancy and poor patient prognosis in gliomas." (PMID 35461228, 2022). "Our study found that BIRC5 expression was increased in low-grade glioma, which was also associated with poor prognosis." (PMID 35309512, 2022). "Through a series of comprehensive approaches, we demonstrated that the upregulated BIRC5 expression is strongly associated with clinicopathologic features, adverse clinical outcomes, and immune cell infiltration in low-grdae glioma." (PMID 35309512, 2022). "ROC curve analysis showed that the BIRC5 expression level has diagnostic value for gliomas." (PMID 35309512, 2022). "Moreover, the KM survival curve analyses showed that upregulated BIRC5 expression associated with adverse clinical outcomes in glioma from both TCGA and CGGA datasets." (PMID 35309512, 2022). "Mechanism studies suggest that 13 can induce apoptosis in glioma cells and suppress proliferation by downregulating BIRC5 expression." (PMID 40076568, 2025). "In the setting of ionizing radiation, the downregulation of the inhibitor of apoptosis protein by siRNA in T98 glioma cells yields significant cellular destruction, compared to a lack of apoptosis evident with ionizing radiation and intact BIRC5 protein." (PMID 40422257, 2025). "In these glioma cell lines, we further demonstrated that ICG-001 downregulated the CBP/β-catenin target gene Survivin/BIRC5–a hallmark of Wnt/CBP/β-catenin inhibition." (PMID 38449858, 2024). "Consistent with previous reports, our results showed that BIRC5 upregulation can promote the proliferation and migration of glioma cells, and scutellarin can significantly inhibit or even block these." (PMID 37340587, 2023). "This original research showed that scutellarin can promote the apoptosis of glioma cells and inhibit the proliferation by downregulating the expression of BIRC5." (PMID 37340587, 2023). "In order to further prove that scutellarin can target and regulate BIRC5, BIRC5 was overexpressed in scutellarin treated glioma cells." (PMID 37340587, 2023). "In the present study, scutellarin was proven to have significant anti‐glioma effects, and BIRC5 was reported as an oncogene of glioma." (PMID 37340587, 2023). "And then qPCR was performed to detect the expression of BIRC5 in glioma tissues, cells and normal brain tissues and glial cells." (PMID 37340587, 2023). "BIRC5 downregulation significantly inhibits the proliferation of glioma cells, in which glioma cell apoptosis is activated." (PMID 37340587, 2023). "As compared with HEB normal glial cells, scutellarin also significantly decreased the expression level of BIRC5 in glioma cells." (PMID 37340587, 2023). "This study improves our understanding of the correlation between BIRC5 and low-grade glioma, but some limitations still exist." (PMID 35309512, 2022). "UBE2C, BIRC5, and CCNB2 were reported to be oncogenic and are associated with several cancers including glioma." (PMID 36105094, 2022). "In summary, we found that BIRC5 was significantly aberrantly overexpressed in glioma tissues and cells." (PMID 35309512, 2022). "For the biological function on the glioma cells, we found that BIRC5 was highly expressed in glioma cell lines, depletion of BIRC5 significantly inhibiting the migration of glioma cells." (PMID 35309512, 2022). "The resultant depletion of BIRC5 was found to significantly inhibit glioma cell migration by transwell and wound healing assays." (PMID 35309512, 2022). "To identify signaling pathways that are affected by BIRC5 overexpression in glioma, we performed a gene set enrichment analysis (GSEA)." (PMID 35309512, 2022).